LEP (leptin)
Diseases named in the same sentence as LEP in open-access papers (continued):
Sharing a sentence is not in itself a finding about the gene and the disease.
diabetes (continued). "This indicates greater time-specific downregulation of leptin signalling before and during diabetes, and may have contributed to the greater disease severity in HOM mice." (PMID 31601900, 2019). "Patients with CGL and BSCL2 variants have lower leptin levels and an earlier onset of diabetes than those without these variants." (PMID 29704234, 2019). "It has also been hypothesized that in diabetes, obese-related diastolic heart failure, the synthesis of leptin leads to sodium retention and plasma volume expansion along with increased cardiac and renal fibrosis." (PMID 30935417, 2019). "The additional adjustment for BMI did not take statistical significance away from the rs17451107-CCNL1, which remained associated with plasma leptin levels even after a later adjustment in model 3 for diabetes (p = 0.0014, not shown)." (PMID 31766143, 2019). "Among the participants, thirty-eight of them who were in the high arterial stiffness group, had a higher prevalence of diabetes mellitus (p = 0.002), age (p = 0.029), body mass index (BMI, p = 0.018), body fat mass (p = 0.001), hemoglobin (p = 0.040), and serum leptin levels (P<0.001)." (PMID 29304064, 2018). "Furthermore, GLP-1 levels were higher in the diabetes group (p = 0.02), whereas leptin, glucagon, and GIP levels were similar between the two groups." (PMID 29467719, 2018). "Increased concentrations of insulin, C-peptide and leptin have been associated with increased intra-abdominal fat, in both the short and long term, in Japanese-Americans without diabetes." (PMID 30555835, 2018). "Leptin promotes the release of active macrophage lipoprotein lipase via an oxidative stress-dependent pathway, signifying a proatherogenic effect of leptin on macrophages in diabetes." (PMID 29643982, 2018). "Fasting plasma levels of glycated hemoglobin, leptin, pro-insulin and retinol binding protein 4 differed between impaired fasting glucose/impaired glucose tolerance and normal subjects group and between newly detected diabetes and normal subjects group." (PMID 29610560, 2018). "Factors associated with plasma levels of adiponectin and leptin were studied in adult subjects without diabetes from Cotonou in Benin (West‐Africa)." (PMID 29890036, 2018). "Alterations in adipokines secretion such as leptin and adiponectin could play an important role in the diet-induced diabetes." (PMID 29755549, 2018). "miR-146a-5p was increased by 2.8-fold in islets of leptin-deficient ob/ob obese diabetes-resistant mice compared with lean mice, but only induced by 1.2-fold in diabetes-prone non-diabetic mice." (PMID 30260972, 2018). "A recent systematic analysis showed that high leptin levels were associated with diabetic neuropathy, including autonomic neuropathy, independent of BMI and diabetes duration." (PMID 29329523, 2018). "There was a trend for association of Dialister with circulating leptin and oxytocin in subjects without diabetes." (PMID 29596446, 2018). "Furthermore, despite leptin signaling blocking having been related to diabetes development in rodents, it seems to be less critical in humans." (PMID 30082375, 2018). "However, the mechanisms responsible for the effects of hypophysectomy on HR and BP regulation in diabetes and during chronic leptin infusion are uncertain and await further investigation." (PMID 29190687, 2017). "Moreover, in the present paper a positive high correlation has been indicated between the leptin concentration in the blood plasma of diabetics, both the untreated and those subject to insulin therapy, and the body mass index of the studied individuals." (PMID 28758947, 2017). "Moreover, many other parameters (eg insulin and leptin) were suggested to be used as indicators or predictors for diabetes status or its glycemic control." (PMID 28127544, 2017).
diabetes (continued). "Mmp12, part of the inflammatory matrix metalloproteinase family, was up‐regulated in the SCN 143‐fold during diabetes but unaffected by pioglitazone treatment, supporting our previous study which demonstrated Mmp12 up‐regulation in the SCN of leptin‐deficient BTBR ob/ob mice." (PMID 28272773, 2017). "Unraveling the mechanisms by which leptin regulates glucose and BP may lead to new therapeutic approaches for treatment of diabetes and other metabolic disorders as well as hypertension." (PMID 29190687, 2017). "The leptin-resistant db mouse was employed for investigation of glutaredoxins in diabetes." (PMID 28542222, 2017). "The obtained results in this paper pointed out a high negative correlation between the concentration of the mentioned receptor and the concentration of its ligand, leptin, in the blood plasma of diabetics both before treatment and after application of the therapy." (PMID 28758947, 2017). "A meta-analysis of 11 prospective cohort studies showed that diabetes risk significantly increased by 37% per 1-log ng/mL increment in leptin levels in men but not in women." (PMID 28786989, 2017). "Regardless of diabetes status, maternal HbA1c at delivery was associated with weight Z-score, skinfold and leptin concentrations." (PMID 28750045, 2017). "Therefore, the aim of this study is to investigate the effect of maternal diabetes on adipocytokines (adiponectin, leptin and TNF-α) production in F1 offspring in rats, as a potential mechanism for the transgenerational effect of maternal diabetes." (PMID 28078101, 2017). "Therefore, our study aimed to assess the effect of a commercially available bee honey (1 g/kg/day for 4 weeks) on the concentrations of blood glucose, insulin and leptin and body weight in normal rats and rats with streptozotocin-induced diabetes." (PMID 28127544, 2017). "The obtained results indicated that, in the blood plasma of patients suffering from diabetes, both the untreated and the treated, leptin occurs in significantly higher concentrations in relation to the concentration of this protein in the blood plasma of the individuals from the control group." (PMID 28758947, 2017). "In 2014, leptin injections were approved by the United States and other countries for the treatment of congenital leptin deficiency and generalized lipodystrophy; however, the current methods of leptin delivery impede its use for the general population of patients with diabetes." (PMID 27055280, 2016). "Leptin treatment appears to be beneficial in such a circumstance, thus this treatment might also be considered in some human diabetes patients with diminished insulin reserve." (PMID 28702245, 2016). "We show that a Palaeolithic diet results in significantly lower fasting plasma leptin, non-significantly lower fasting plasma glucagon concentrations as well as weight loss, compared to a standard diabetes diet." (PMID 27216013, 2016). "In our study there was a non-significant lower fasting glucagon levels after the Palaeolithic diet compared to the diabetes diet, which could be a result of the amelioration of leptin sensitivity in the pancreatic islets." (PMID 27216013, 2016). "In diabetes, leptin function may be modulated by a number of factors, including the ratio between free and bound leptin, local leptin levels, the expression of different forms of the receptors, and the presence of specific inhibitors and inflammation." (PMID 26432692, 2016). "Compared to the existing ob/ob mouse models, this Lep∆I14/∆I14 rat strain provides a robust tool for further dissecting the roles of LEP in the diabetes related kidney disease and reproduction problem, beyond its well established function in regulating energy homeostasis." (PMID 27378381, 2016). "It has been recently demonstrated that leptin can reverse diabetes." (PMID 26090474, 2015).
diabetes (continued). "In a large study of 5,820 participants from the United States Third National Health and Nutrition Examination Survey (NHANES III), higher plasma leptin concentrations were found to be associated with CKD after adjusting for age, gender, ethnicity, BMI, diabetes, hypertension, and serum cholesterol." (PMID 25793395, 2015). "The Ghanaian men had the lowest mean insulin and leptin levels (79.8 ± 28.1 pmol/L and 4.9 ± 6.3 μg/L, respectively), while the US men had the highest insulin, leptin, as well as percentage participants with diabetes (138.0 ± 91.4 pmol/L, 11.2 ± 13.4 μg/L, and 6.7 %, respectively)." (PMID 26374293, 2015). "Multiple regression analysis showed that plasma leptin was significantly associated with SDNN and SDANN5 independent of other factors, including age, gender, presence of hypertension and dyslipidemia, duration of diabetes, HbA1c, and eGFR." (PMID 26338087, 2015). "While the precise relationship between leptin, adiponectin, and HCC is still poorly understood, the chronic inflammation associated with diabetes may also promote HCC." (PMID 26441826, 2015). "Leptin is one of the most studied adipocytokines, and its peripheral level has been demonstrated to be substantially increased in obese humans, as well as in patients with diabetes." (PMID 25948792, 2015). "Adiponectin and leptin are relatively prevalent, and are occasionally used in diabetes screening." (PMID 26132231, 2015). "Thus we prospectively studied leptin levels in relation to ischemic heart disease in middle aged patients with type 2 diabetes mellitus." (PMID 25994184, 2015). "We used backward elimination (where all the candidate variables are initially included, and variables are removed when such deletion improves the model), with CSF 2-AG as the dependent variable and with age, gender, incidence of diabetes, BMI and CSF leptin as the independent variables." (PMID 25835291, 2015). "In addition, leptin levels reflect the amount of stored fat and degree of energy imbalance in diabetes." (PMID 26198246, 2015). "The coding product of LEP, leptin, is closely related to body weight regulation and its deficiency in mice and human causes morbid obesity and diabetes, while the role of MIR129 in diabetes remains unknown." (PMID 24864266, 2014). "Some studies showed that the decreased serum leptin may also participate in the accelerated gastric emptying of early diabetes." (PMID 24860604, 2014). "Leptin is associated with body mass index (BMI) and body fat in non-obese and obese subjects and in patients with Type 2 diabetes mellitus." (PMID 23853613, 2013). "Administration of leptin or AMPK activators can effectively prevent the development of diabetes." (PMID 24455748, 2013). "Secondary features are atlantoaxial instability, hepatomegaly, mild metabolic complications such as high circulating triglycerides and hyperinsulinism or diabetes, low leptin and adiponectin levels, reduction of growth hormone levels, immunoglobulin A deficiency, and umbilical prominence." (PMID 24024685, 2013). "Indeed, obese (ob) leptin-deficient mice on the C57BL/6J background are infertile and initially obese, but then lose weight and die prematurely due to severe diabetes with islet β-cell failure." (PMID 24278193, 2013). "There are few clinical reports on the effect of leptin therapy on diabetes." (PMID 23579596, 2013). "For example, leptin and insulin act on the hypothalamus to regulate energy balance and hepatic gluconeogenesis, and therefore, appear to control fasting hyperglycemia in diabetes." (PMID 23991090, 2013). "In the other clinical study, two lipoatrophic diabetes patients received leptin therapy." (PMID 23579596, 2013). "This study aimed to investigate the association of blood concentrations of leptin, ghrelin and inflammatory cytokines with body mass index (BMI) in TB patients with and without type 2 diabetes mellitus (T2DM)." (PMID 24260344, 2013).
diabetes (continued). "Of note, changes in the adiponectin/leptin balance in the course of diabetes may first be seen by utilizing measures of high-molecular weight adiponectin rather than total adiponectin, as demonstrated by our findings." (PMID 22110481, 2012). "Alterations in offspring leptin levels are another possible underlying mechanism, but fasted leptin levels were not significantly altered by exposure to diabetes in Akita mice." (PMID 23209676, 2012). "Both adiponectin and leptin increased with progression of diabetes in this study." (PMID 22110481, 2012). "Also, it has recently shown that the levels of resistin are correlated to those of leptin and that both these adipokines induce increased procoagulability in diabetes mellitus." (PMID 22745767, 2012). "There is a significant effect (p<0.05) of maternal or paternal diabetes (group) on most metabolic markers studied in offspring, including: weight, length, fasted glucose, glucose clearance after ip glucose challenge (AUC), and leptin." (PMID 23209676, 2012). "The model of diabetes used in the present study was dependent upon abnormal leptin signaling which might contribute to vascular dysfunction." (PMID 23346101, 2012). "At the other hand changes in leptin or other adipokines as occur in diabetes may also play a role in the observed changes in the ARC." (PMID 22808091, 2012). "By 26 weeks of age leptin levels were significantly decreased in offspring of paternal diabetes." (PMID 23209676, 2012). "Recently, a large prospective cohort reported a strong inverse association between sOB-R and diabetes, independent of BMI, leptin and adiponectin." (PMID 21347230, 2011). "Linear mixed models were used to study the effects of longitudinal leptin changes on changes in nutritional parameters (slopes) over 24 months including fixed parameters such as age, gender, diabetes status, dialysis vintage, previous cardio-vascular events, and fat mass." (PMID 21676262, 2011). "Analysis of each of these variables by age showed a significant age trend for BMI, waist-hip ratio (marker of central adiposity), alcohol use, systolic blood pressure, elevated cholesterol, prevalence of diabetes, leptin, adiponectin, IL-6, bilirubin, and albumin with increasing age." (PMID 21170382, 2010). "Of paramount interest has been thepotential interaction(s) between leptin and insulin.Insofar as insulin alters leptin secretion/action (orvice versa), dysregulation of this system could contributeto disease states such as diabetes." (PMID 12369715, 2001). "Using PROCESS version 4 for SPSS (model 4) with 5000 bootstrap resamples, we examined whether waist circumference mediated the association between leptin and VRI, while adjusting for age, height, body weight, eGFR, HDL-C, diabetes history, and smoking (p < 0.2)." (PMID 41470134, 2025). "Subsequently, it was demonstrated that fat transplantation in lipoatrophic mice with clinical symptomatology of CGL allowed for the reversal of diabetes, and the metabolic disturbances found in lipodystrophic mice and humans could be attenuated by administering leptin." (PMID 40508223, 2025). "Thus, ghrelin and leptin, along with insulin, may be interrelated in diabetes-induced changes in food intake and independent alterations in ghrelin levels." (PMID 41195415, 2025). "Additionally, both TS and diabetes might share a common pro-inflammatory profile, characterized by elevated levels of inflammatory cytokines, cortisol, and leptin, which can promote the development of both metabolic disorders and neuropsychiatric conditions." (PMID 40094948, 2025). "It is worth noting that even though individuals with typical diabetes or lipid abnormalities often exhibit significant reductions in adiponectin and elevations in leptin, early compensatory mechanisms may happen in generally healthy individuals or animal models." (PMID 41048434, 2025).
diabetes (continued). "Additionally, leptin levels may vary with the duration and severity of diabetes, yet very few studies have examined leptin concentrations in newly diagnosed cases." (PMID 40630340, 2025). "This theory is further supported by our data as higher leptin (or body fat) levels were important for predicting low NT-proBNP levels in women with normal glucose tolerance, while impaired insulin sensitivity was the most important factor after developing prediabetes/diabetes." (PMID 39097697, 2024). "Hypertension and diabetes, but not leptin, mediated the association of BMI and TBF with CKD." (PMID 38627329, 2024). "Disruption of this equilibrium may lead to metabolic disturbances, insulin and leptin resistance coexist in diabetes, obesity and CVD due to both of them share the same signal transduction pathways such as protein tyrosine phosphatase 1B (PTP1B) and suppressor of cytokine signaling 3 (SOC3)." (PMID 39538244, 2024). "Furthermore, we found a statistically higher concentration of leptin in the group of children with newly diagnosed diabetes compared to children from the diabetic group with poor metabolic control and lower than healthy children (11.19 vs. 7.84 and 20.94 ng/mL)." (PMID 37670877, 2023). "MicroRNAs may be involved in changes in leptin-signaling activation in diabetes." (PMID 36674935, 2023). "Also, leptin and insulin regulate each other in blood‐glucose homeostasis, whereby restricted leptin signaling can induce hyperglycaemia and hyperinsulinemia, ultimately leading to diabetes mellitus." (PMID 37920118, 2023). "Leptin was recently approved by the Food and Drug Administration (FDA) for the treatment of lipodystrophy, considering that leptin treatment may enhance positive regulators of muscle cell proliferation along with correcting infertility, diabetes, and immune abnormalities." (PMID 37058498, 2023). "Similarly to IR in diabetes, impaired response to leptin seems to be selective." (PMID 37446161, 2023). "Another clinical study that aimed to assess the impact of cumin EO and vitamin E on the lipid profile and blood levels of leptin and HbA1C in individuals with diabetes showed that 25 mg of cumin EO per day has a greater effect and is superior to vitamin E in terms of lowering the diabetes index." (PMID 38003691, 2023). "However, the role of leptin in the development of diabetes remains controversial." (PMID 37371552, 2023). "In conclusion, our study showed that leptin SR is higher in patients with T2DM and is associated with abnormal β-cell function and thus it might be considered as an important marker in the pathogenesis of diabetes." (PMID 36950695, 2023). "Pioglitazone (PIO), a diabetes drug, improves the effect of insulin/leptin in the hypothalamus, partly by activating the Adipo/AdipoR1/AMPK axis in the hypothalamus, suggesting that Adipo and AdipoR1 may play an important role in improving the effect of IR in hypothalamus." (PMID 37034166, 2023). "Additionally, higher leptin levels were linked to a higher incidence of type two diabetes mellitus in a five-year prospective analysis of white men without diabetes." (PMID 37238961, 2023). "Secretion of adipokines including leptin and resistin is altered in adipose tissue dysfunction and may contribute to diabetes, which may provide promising novel pharmacological treatment strategies for diabetes." (PMID 34996484, 2022). "Additionally, the lack of tonic suppression of insulin secretion by leptin, leads to increased insulin production by pancreatic beta cells, which then results in pancreatic beta cell dysfunction – a major cause of type 2 diabetes mellitus." (PMID 36381191, 2022). "The same pathway was found to be involved in central regulation of leptin signaling as displayed in mice with neural-specific disruption of STAT3, which recapitulated the phenotype typically observed in leptin resistance (i.e., hyperphagia, diabetes) in association with an increase in infertility." (PMID 35897769, 2022).